IL6 (interleukin 6)
Diseases named in the same sentence as IL6 in open-access papers (continued):
Sharing a sentence is not in itself a finding about the gene and the disease.
multiple sclerosis (continued). "Consistently, the expression of inflammatory cytokines such as IL-8 and TNF-α in diabetic patients and IL-6, IL-8, CSF2 and TNF-α in multiple sclerosis patients increased." (PMID 31294790, 2019). "IL-6-expressing CD19+ B lymphocytes were significantly increased in patients with a diagnosis of either PP, SP and RR multiple sclerosis compared to BEMS individuals and HC, with the highest values being present in PPMS patients." (PMID 27412504, 2016). "One of the most common adverse event of interferon beta (IFNβ) therapy for multiple sclerosis is flu-like syndrome (FLS), which has been reportedly related to increased levels of cytokines such as interleukin 6 (IL-6) and tumor necrosis factor-alpha (TNF-α)." (PMID 26285213, 2015). "The HERV-W syncytin-1 exerted its inflammatory effects by induction of proinflammatory mediators, such as IL-1β, IL-6, IL-12, iNOS, and TNF-α, leading to neuron inflammation in multiple sclerosis patients." (PMID 21772664, 2011). "It was shown that blocking the activity of either IL-23 itself or its downstream factors IL-17 and IL-6 significantly impeded the development of disease in animal models of IBD and multiple sclerosis." (PMID 21253534, 2010). "For the remaining 4 of 22 patients who received combination therapy and whose IL-6 serum level at baseline was not available, 3 patients had lymphoma and 1 had multiple sclerosis treated with anti-CD20 moAbs." (PMID 37097384, 2023). "For example, in animal models of multiple sclerosis, CBD has been shown to have a significant anti-inflammatory effect since it was able to decrease the concentration of proinflammatory cytokines interleukin 6 (IL-6), interleukin 12 (IL-12), tumor necrosis factor α (TNF-α), and interleukin 1 (IL-1)." (PMID 36289755, 2022). "In experimental autoimmune encephalomyelitis (EAE), which is a model for multiple sclerosis, the differentiation of autoreactive TH17 cells is induced by IL-6 and its pathogenicity was demonstrated in IL-6−/− mice which are completely resistant to the induction of EAE." (PMID 33375150, 2020). "Moreover, an interesting study found an inverse correlation between the release of IL-6, IL-8, and VEGF by BM-MSCs from multiple sclerosis patients and the number of white matter lesions in their brains." (PMID 31531025, 2019). "The model was also used to dissect the molecular pathogenesis of inflammatory CNS diseases such as multiple sclerosis, by determining the effect on myelin of cytokines such as tumour necrosis factor-α (TNF-α), interleukin-1β (IL-1β), interleukin-6 (IL-6) and interferon-γ (IFN-γ)." (PMID 18793322, 2008). "Moreover, other groups also described elevated levels of IL-1β or IL-1β/TNF-α induced molecules like IL-1ra, IL-6, IL-8, IL-13, G-CSF, and Cxcl10 (IP-10) in the CSF of NMO patients, compared to the CSF of patients with multiple sclerosis or other neurological diseases." (PMID 24252536, 2013). "Moreover, given the association of elevated IL-6 levels with the pathogenesis of multiple sclerosis and encephalomyelitis —both characterized by demyelination and neurodegeneration—GFAP-IL6 mice may serve as a model to investigate certain neuroinflammatory aspects of these conditions." (PMID 39273398, 2024).
dementia (199 papers, 2004 to 2026). Loss of intellectual abilities interfering with an individual's social and occupational functions. "The ACE, REN, APOE, CRP, and IL6 proteins obtained through this bioinformatic approach appear to be associated with both HF and dementia." (PMID 40699836, 2025). "Although the exact causes of dementia remain multifactorial and complex, oxidative stress (reactive oxygen species), neuroinflammation (TNFα, IL-6, and IL-1β), and inflammasomes are considered central mechanisms in its pathology." (PMID 40277934, 2025). "The adipose tissue is an endocrine organ, capable of secreting inflammatory cytokines, such as interleukin-6 (IL-6), and tumor necrosis factor-α, which are associated with an increased risk of dementia." (PMID 39861366, 2025). "A large UK-Biobank population study found a significant association between high IL-6 levels, cortical and subcortical atrophy (including the Hippocampus), and all-cause dementia in the longitudinal analysis." (PMID 40606939, 2025). "In men that developed dementia the serum IgG levels were associated with elevated levels of cytokines, and in particular IL12p70, IL-8, IL-6 and TGFβ." (PMID 41384827, 2025). "Inflammatory markers C-reactive protein (CRP) and interleukin-6 (IL-6), which are also often elevated following a fracture, have been associated with an increased risk of all-cause dementia." (PMID 38334917, 2024). "Studies have shown that levels of inflammatory markers, such as TNF‐α, IL‐6, and C‐reactive protein, elevate before the manifestation of clinical symptoms associated with various types of dementia, including AD and vascular dementia." (PMID 38482136, 2024). "A meta-analysis evaluating the association between peripheral IL-6 levels in all-cause dementia found that higher concentrations of this inflammatory marker conferred an increased risk of developing AD." (PMID 38933077, 2024). "Of these three inflammatory markers, CRP has been associated with progression to dementia even after adjustment for confounding factors, while IL-6 has been specifically associated with vascular dementia." (PMID 37239136, 2023). "A meta-analysis including 28 observational studies found that biomarkers associated with dementia, such as elevated blood-based levels of IL-6, C-reactive protein, S100B, and NfL, were also associated with delirium." (PMID 37550780, 2023). "In contrast, B cells isolated from Parkinson’s disease patients at higher risk of dementia had greater cytokine (interleukin 6 and interleukin 10) responses following in vitro stimulation." (PMID 36993946, 2023). "In contrast, B cells isolated from PD patients at a greater risk of dementia exhibited increased levels of IL-6 and IL-10." (PMID 38020762, 2023). "Further, one meta-analysis found that C-reactive protein level was associated with the risk of dementia, while another study found an association between IL-6 level and the risk of dementia." (PMID 37480061, 2023). "We identified the strongest interactions between combinations of SNPs (IL-6 rs1800796, TNFα rs361525, and IFNγ rs2069705) associated with the risk of suffering from dementia." (PMID 36389080, 2022). "Accordingly, a previous meta-analysis study indicated that inflammation markers like Interleukin-6 and C-reactive protein are related to an enhanced risk of dementia." (PMID 35444524, 2022). "Of the estimated genotypic pools, individuals with homozygous alleles for the IL-1α (rs1800587), IL-6 (rs1800796), TNFα (rs361525), and IFNγ (rs2069705) genes were identified in the high-risk group for dementia." (PMID 36389080, 2022).
dementia (continued). "Our finding supports a protective effect of the C allele in the IL-6 gene on dementia risk, which can favor the liberation of IL-6 protein release in the brain, playing an important role in the neuroinflammatory cascade and the pathology." (PMID 36389080, 2022). "It was found that elevated levels of inflammatory markers such as C-reactive protein (CRP) and Interleukin-6 (IL-6) are associated with loss of skeletal muscle mass, strength and an increased risk for dementia." (PMID 35794312, 2022). "Inflammation and oxidative stress are implicated in the pathogenesis of dementia; there is evidence suggesting that the loss of skeletal muscle is associated with high levels of inflammatory markers such as interleukin-6 and CRP." (PMID 35013908, 2022). "Another avenue for further research are inflammatory markers such as C-reactive protein, interleukin-6, and α1-antichymotrypsin, which have shown predictive value for the onset of all-cause dementia." (PMID 32116848, 2020). "Among 1841 participants aged 65 to 80 community-dwelling elderly free of dementia, higher IL-6 levels were associated with lower gray matter and hippocampal volumes, and increased CSF volumes in a dose-relationship pattern." (PMID 32000805, 2020). "The relationship between higher levels of IL-6 and increased risk of dementia was presented in a meta-analysis." (PMID 32455758, 2020). "For IL-6, baseline dementia modified this association (interaction p-value = 0.1826) such that higher concentrations of IL-6 were more prominently associated with longer ED delirium duration in patients without dementia (POR = 1.59, 95%CI: 1.09–2.32)." (PMID 31856187, 2019). "In a 7‐year long observational study conducted in participants with vascular risk factors, those with higher circulating levels of IL‐6 were more likely to develop dementia." (PMID 31660705, 2019). "Systemic inflammation is associated with neurodegeneration, with elevated interleukin-6 (IL-6) in particular being correlated with an increased risk of dementia." (PMID 27347374, 2016). "Several population-based studies have shown that peripheral inflammatory cytokines, especially IL-6, TNFα, and IL-1β, are correlated with the risk of dementia." (PMID 27340344, 2016). "In the literature involving elderly individuals, the associations between IL-6 and dementia are controversial." (PMID 24133408, 2013). "Recently, an association between inflammatory markers alpha 1-antichymotrypsin, interleukin 6, and, to a lesser extent, C-reactive protein were associated with an increased risk of dementia." (PMID 15476562, 2004). "Furthermore, MAP improved inflammatory biomarkers such as CRP, IL-6 and IL-1β, showing its potential to target biological pathways associated with dementia." (PMID 40563752, 2025). "Our study aimed to evaluate inflammatory cytokines CSF IL-6 and IL-17A in patients with vascular cognitive impairment of the subcortical small-vessel disease subtype in order to discriminate vascular from neurodegenerative causes of dementia, particularly AD." (PMID 40150012, 2025). "If considering treatment resistance and consistent evidence via meta-analysis of cytokine change in MDD and dementia, only IL6, TNF, and CRP are implicated, though this may reflect the relative popularity of these molecules for study." (PMID 38175420, 2024). "Additionally, the TNF-α released from microglia, in conjunction with IL-6, has been linked to late-onset dementia and a greater risk of dementia." (PMID 39104536, 2024). "Longitudinal studies are needed in order to assess whether IL-6 levels are suitable as a diagnostic tool in order to identify individuals at high risk for dementia." (PMID 36915478, 2023). "However, as our study is a cross-sectional research design, we cannot establish a cause–effect relationship between IL-6 levels and the onset or progression of dementia." (PMID 37489445, 2023).
dementia (continued). "Moreover, increased C-reactive protein and IL-6 are associated with dementia, identified by a meta-analysis combining seven observational studies (5,717 participants and 746 dementia cases)." (PMID 36344931, 2022). "Similarly, IL-6 rs1800796 showed a risk effect on the susceptibility to dementia under the additive model (OR = 2.066, 95%; CI = 1.51–2.82; p = 0.001)." (PMID 36389080, 2022). "IL-6 had a significant effect on dementia in patients with vascular risk factors." (PMID 34421513, 2021). "In addition, it was shown that elevated levels of IL-6 contribute to the insurgence of dementia in patients with vascular risk factors." (PMID 31096580, 2019). "Other biomarkers of risk to dementia, such as the presence of ApoE4 and inflammatory markers (IL6, CRP), may be associated with a steeper decline on cognitive status or greater neuronal loss." (PMID 25685779, 2015). "In a longitudinal analysis of blood from approximately 900 subjects, higher protein levels of three inflammatory markers (interleukin 6, α1-antichymotrypsin, and C reactive protein) were associated with an increased risk of dementia in general and of AD specifically." (PMID 23705665, 2013). "Biomarkers linked to dementia neuropathology (e.g., hyperphosphorylated tau, amyloid beta), neuronal injury (e.g., total tau, neurofilament light chain), glial activation (e.g., glial fibrillary acidic protein), and systemic inflammation (e.g., interleukin-6) have shown promise." (PMID 40951922, 2025). "In addition, a longitudinal study of the effects of dementia care stress on caregivers’ health by Von Känel expresses that family caregivers of patients with dementia had higher plasma interleukin-6 and D-dimer levels, which in turn led to an increased risk of CVDs." (PMID 35571163, 2022). "Additionally, TNF-α together with other cytokines (e.g., IL-6) associate aging and dementia." (PMID 32802484, 2020). "Of the genes/proteins associated with dementia, six are consistent with the results obtained from VOSviewer: APP, MAPT, APOE, ACE, IL6, and CRP." (PMID 40699836, 2025). "Higher preoperative blood NfL and GFAP levels independently predicted POD after adjusting for age, sex, dementia, frailty, and Interleukin-6 (Odds Ratio, OR: 3.21, 95% Confidence Interval, CI: 1.26-8.21, and OR: 3.66, 95% CI: 1.38-9.68, respectively)." (PMID 40354379, 2025). "Dementia and/or MCI was associated with higher serum IL-6, IL-8, and IFN-γ at baseline, and IL-8 and TGF-β at follow-up." (PMID 41384827, 2025). "Elevated levels of IL-6, CRP, and ACT in blood samples have been associated with an increased risk of developing dementia." (PMID 41294487, 2025). "Secondly, higher SB levels were associated with higher levels of CRP, interleukin 6, tissue plasminogen activator which are the marker of inflammation-induced diseases such as cancer, CAD, COPD, dementia." (PMID 40177096, 2025). "We explored the association of AD blood biomarkers with chronic diseases and systemic inflammation (interleukin‐6 [IL‐6]), in 2366 dementia‐free participants of the Swedish National Study on Aging and Care‐in Kungsholmen, using quantile regression models." (PMID 38717935, 2024). "For instance, increases in systemic levels of the inflammatory markers IL-6 and CRP are associated with MCR, a condition involving a remarkable risk of progression toward dementia." (PMID 38337499, 2024). "We prospectively investigated 16 different immune cell phenotypes using flow cytometry and IL-6 in relation to survival outcome among dementia-free Framingham Heart Study (FHS) offspring cohort participants who attended the seventh exam (1998–2001)." (PMID 38867269, 2024). "Further, there is a correlation between elevated levels of interleukin (IL)-6 and C-reactive protein (CRP) and chronic low-grade inflammation, which, in turn, increases the risk of all-cause dementia by 37% and 40%, respectively." (PMID 39193464, 2024).
dementia (continued). "In future studies, it would also be interesting to consider the relationship between IL-6 and dementia." (PMID 37489445, 2023). "In Mexico, less has been explored about the relationship of the genes’ pro-inflammatory cytokines released from activated microglia (IL-1α, IL-6, TNFα, and IFNγ) with dementia." (PMID 36389080, 2022). "This study aimed to evaluate the effect of epistasis of gene cytokines such as interleukin (IL)-α, IL-6, tumor necrosis factor (TNFα), and interferon-gamma (IFN-γ) on the susceptibility to the development of dementia." (PMID 36389080, 2022). "For instance, elevated levels of inflammatory proteins, α1-antichymotrypsin (ACT) and interleukin-6 (IL-6), were found in the blood plasma of AD patients before clinical onset of dementia." (PMID 35693341, 2022). "We investigate the combinatorial effect of four (IL-1α, IL-6, TNFα, and IFN-γ) genetic polymorphisms involved in the inflammatory processes of microglial cells in the brain on the susceptibility to dementia in Mexican individuals." (PMID 36389080, 2022). "Several studies have found increased levels of pro-inflammatory cytokines and proteins like interleukin-6 (IL-6), interleukin-1β (IL-1β), C-reactive protein (CRP), or α1-antichymotrypsin (α1-AT) to be associated with the onset of all-cause dementia." (PMID 36085081, 2022). "First, elevated levels of plasma pro-inflammatory cytokines are found in dementia patients, such as interleukin-6." (PMID 36158553, 2022). "The anti-inflammatory cytokine IL-6 is increased in dementia brains; nevertheless, some studies have demonstrated differential effects." (PMID 36389080, 2022). "When proinflammatory cytokine release from microglia predominates, IL-6 immunoreactivity becomes prominent around Aβ plaques, and IL-6 levels correlate with the degree of dementia." (PMID 36778590, 2022). "It has been found that the levels of inflammation-related markers, such as IL-1β, IL-18, and IL-6, are increased in both DM and dementia patients." (PMID 32425784, 2020). "Serum levels of IL-6 and CRP in patients with acute ischemic stroke and underlying dementia (AIS + D) were significantly higher (p = 0.002 and 0.003, respectively) than in patients with acute ischemic stroke alone (AIS)." (PMID 32758167, 2020). "In postmortem study performed in patients with severe dementia significantly elevated mRNA for IL-6 and TGF-β1 levels in the entorhinal cortex as compared with cognitively normal subjects was reported, whereas IL-1β mRNA was very low." (PMID 31129771, 2019). "A similar finding was observed in elderly individuals with dementia where an increased level of TNFα molecule was positively correlated with sTNFRII, IL-6, and C-Reactive Protein." (PMID 31178745, 2019). "Reports also show that dementia is related to peripheral pro-inflammatory factors released by periodontal inflammatory mediators such as C-reactive protein, IL-6, haptoglobin, TNF-α, and fibrinogen." (PMID 29740354, 2018). "The whole dementia group in comparison with controls was characterized by statistically significant higher levels of pro-inflammatory IL-6 (p = 0.016)." (PMID 28421328, 2017). "IL-6 was present during the early stages of plaque formation and expression of this cytokine was correlated with clinical dementia." (PMID 25807081, 2015). "Future studies with larger cohorts are required to ratify the potential use of IL-6 as a clinical biomarker to distinguish DLB pathology from AD pathology in early dementia stages." (PMID 26434635, 2015). "In accord with animal data, the main results of our study indicate that the pro-inflammatory cytokine IL-6 is significantly elevated in FTLD PGRN+ patients, as a consequence of both the loss of functional PGRN and the development of dementia." (PMID 21645364, 2011).